SLC6A8 (solute carrier family 6 member 8)
Diseases named in the same sentence as SLC6A8 in open-access papers (continued):
Sharing a sentence is not in itself a finding about the gene and the disease.
ovarian carcinoma (2 papers, 2011 to 2022). A malignant neoplasm originating from the surface ovarian epithelium. "Intriguingly, SLC6A8 expression had positive correlation with the overall survival of patients diagnosed with blood, colorectal and ovarian cancer." (PMID 36061183, 2022). "However, SLC6A8 expression was favorably related to the OS in blood, colorectal and ovarian cancer." (PMID 36061183, 2022). "A panel of six genes: CCNE2, DKFZp1312, PPIC, EMP2, MAL2 and SLC6A8 may serve as potential markers for CTC derived from breast, endometrial, cervical, and ovarian cancers." (PMID 21827674, 2011).
pancreatic cancer (2 papers, 2023 to 2025). "Human liver metastases from colorectal and pancreatic cancers have been shown to express higher levels of creatine kinase and SLC6A8, the creatine transporter." (PMID 41404326, 2025). "However, knockdown of SLC6A6 and SLC6A8 did not diminish the promoting effect of GAA on pancreatic cancer cell migration, possibly because these cells have a greater dependence on passive diffusion of extracellular GAA or de novo GAA synthesis than on the expression of SLC6A6 and SLC6A8." (PMID 37370109, 2023).
X-linked intellectual disabilities (2 papers, 2018 to 2025). "Mutations in SLC6A8 are relatively frequent and were found in up to 2% of cases of X-linked intellectual disability." (PMID 30013483, 2018). "Creatine transporter (CRT1) deficiency (CTD, MIM: 300352), due to loss of function variants in solute carrier family 6 member A8 (SLC6A8), is thought to be the second most common class of X-linked intellectual disabilities, and likely is underdiagnosed." (PMID 40781773, 2025).
Alzheimer disease (1 paper, 2024). A progressive, neurodegenerative disease characterized by loss of function and death of nerve cells in several areas of the brain leading to loss of cognitive function such as memory and language. "We found that NSUN7, SLC6A8, CXCL1 and LCN8 were significantly different in groups B compared to A, and SLC1A3 and LCN8 were significantly different in groups C compared to A. NSUN7, a m5C RNA methyltransferase gene, is differentially expressed in Alzheimer's disease patients." (PMID 39185136, 2024).
Arthritis (1 paper, 2024). Inflammation of a joint. "In CEACAM1, YBX3 and SLC6A8, all three genes were found to be overexpressed in patients with arthritis associated with fever." (PMID 38243323, 2024).
asthma (1 paper, 2022). "We found that GATM was significantly expressed in the mouse asthma model, but not GAMT and slc6a8." (PMID 36177049, 2022).
Brain atrophy (1 paper, 2023). Partial or complete wasting (loss) of brain tissue that was once present. "However, the fact that patients with defects in the SLC6A8 gene experience progressive brain atrophy, cognitive disability and speech deficit, which cannot be treated by creatine oral supplementation, indicate an essential role of Crt1 in maintaining optimal brain creatine levels." (PMID 40084065, 2023).
colon adenocarcinoma (1 paper, 2022). "Interestingly, 3 types of cancer, including colon adenocarcinoma (COAD), pheochromocytoma and paraganglioma (PCPG) and Rectum adenocarcinoma (READ), exhibited significantly lower SLC6A8 expression as compared to their respective normal tissues." (PMID 36061183, 2022).
folate deficiency (1 paper, 2021). A nutritional condition produced by a deficiency of FOLIC ACID in the diet. "Thiamine and biotin treatment in biotin- or thiamine-responsive encephalopathy (mutations in SLC19A3), folinic acid in cerebral folate deficiency (mutations in FOLR1), and creatine in cerebral creatine deficiency (mutations in SLC6A8) are other examples." (PMID 33726816, 2021).
GAMT deficiency (1 paper, 2012). "Three additional affected sibs were identified after familial inquiries (1 brother affected with GAMT deficiency and 2 brothers with SLC6A8 deficiency in two different families)." (PMID 23234264, 2012).
gastric cancer (1 paper, 2021). A primary or metastatic malignant neoplasm involving the stomach. "Among the 10 target genes, the expression of MYLK, RET and SLC6A8 was down regulated in gastric cancer, while the expression of the other 7 genes was up-regulated in gastric cancer." (PMID 34249673, 2021).
hearing loss (1 paper, 2022). "Another SLC6 family member, SLC6A8, encoding the creatine transporter, was also found to be associated with hearing loss." (PMID 35154281, 2022).
hepatocellular carcinoma (1 paper, 2023). A malignant tumor that arises from hepatocytes. "Analysis of literature data showed that an elevated level of SLC6A8 was noticed in breast, non-small cell lung or hepatocellular cancers." (PMID 36835201, 2023). "Study on human hepatocellular carcinoma cells (Huh-7 and Hep3B) with knockdown of the SLC6A8 gene showed that the lack of transporter leads to decrease of proliferation, induction of apoptosis, blockage of cell migration, and invasion." (PMID 36835201, 2023).
inflammatory bowel disease (1 paper, 2024). A spectrum of small and large bowel inflammatory diseases of unknown etiology. "SLC6A8 regulates the energy balance of intestinal epithelial cells, thereby regulating intestinal epithelial integrity and barrier function, which leads to intestinal barrier dysfunction in patients with inflammatory bowel disease." (PMID 38243323, 2024).
ischemic stroke (1 paper, 2020). A stroke disorder caused by obstruction of blood flow to the brain, due to thrombotic (local blood clot formation) or embolic (due to a blood clot or other material traveling from another site) event. "The analysis revealed a significant upregulation of Bcas1 and Slc6a8 after ischemic stroke." (PMID 32182846, 2020).
liver failure (1 paper, 2020). A liver disease characterized by the liver losing or has lost all of its function.
neuroblastoma (1 paper, 2010). Neuroblastoma (NB) is the most common solid, extracranial childhood tumor. "BCL11B, which was previously shown by microarrays and rt-PCR to be downregulated in PD blood was also downregulated in rotenone-treated neuroblastomas, and so was the creatine neurotransmitter transporter SLC6A8." (PMID 20161708, 2010).
Primary amenorrhea (1 paper, 2022). "The patient phenotype at the age of 22 was in accordance with previous reports, except that she had also had primary amenorrhea.The SLC6A8-gene codes for a sodium- and chloride-dependent transporter carrying creatine across the blood-brain-barrier." (PMID 35979408, 2022).
steatosis (1 paper, 2021). Increased lipid within the cytoplasm of cells. "Of note, the summed expression of SLC6A6 and SLC6A8 was positively associated with IHTG %, suggesting that their expression increases with steatosis (p = 0.04)." (PMID 34192533, 2021).
Type 2 Diabetes (1 paper, 2021). "We used the Accelerating Medicines Partnership Type 2 Diabetes Knowledge Portal to understand the effect of missense mutations in genes encoding the hepatic GABA transporters (SLC6A6, SLC6A8, SLC6A12, and SLC6A13)." (PMID 34192533, 2021).
ulcerative colitis (1 paper, 2023). An inflammatory bowel disease involving the mucosal surface of the large intestine and rectum. "SLC6A8 loss in knockout mice resulted in impaired barrier formation, and in, ulcerative colitis patients, a disease hallmarked by barrier defects, SLC6A8 is downregulated compared to in healthy colon." (PMID 36793710, 2023).
tumor (20 papers, 2010 to 2026). "Further, tumor-derived sEVs inhibit CD8+ T cell SLC6A8 (solute carrier family 6 member 8) dependent creatine import in NPM-1 mutated AML cells through the transfer of miR-19a-3p." (PMID 37822925, 2023). "Lately, it has been reported that SLC6A8 is implicated in the malignant progression of various tumor." (PMID 36061183, 2022). "SLC6A8 expression was found to be negatively associated with the majority of tumor-infiltrating immune cells in most of the cancers such as BRCA, UCS, LUSC, SKCM, KIRP, and KICH." (PMID 36061183, 2022). "Studies have shown that SLC6A8 is not only associated with tumor development, but is also involved in the tumor immune microenvironment (TIME)." (PMID 35692837, 2022). "An analysis of the association between SLC6A8 and the tumor immune microenvironment (TIME) of LUAD was performed through the TISIDB database and estimation of stromal and immune cells in malignant tumor tissues using expression data (ESTIMATE) algorithm." (PMID 35692837, 2022). "We found that tumor-infiltrating immune cells (TIIs) up-regulated their expression of the creatine transporter gene (Slc6a8 or CrT), which encodes a surface transporter controlling the uptake of creatine into a cell." (PMID 31628186, 2019). "When studying nutrient usage of tumor-infiltrating immune cells in mice, we detected a sharp increase of the expression of a CrT (Slc6a8) gene, which encodes a surface transporter controlling the uptake of creatine into a cell." (PMID 31628186, 2019). "While our multi‐omics study shows elevated creatine levels and overexpression of the associated transporter protein SLC6A8 in primary SqCC tumor tissue, the source behind the actual increased creatine levels in patient tumor tissue remains to be further investigated." (PMID 40903981, 2025). "Moreover, we analyzed the top 100 genes that were associated with SLC6A8 expression based on tumor data from GEPIA2." (PMID 36061183, 2022). "When comparing bulk tumor tissue to matched normal tissue, the increased mRNA expression of the creatine transporter SLC6A8 gene and decreased CHKA expression appeared tumor‐associated." (PMID 40903981, 2025). "In this study, we found that under hypoxic conditions, tumor cells upregulate SLC6A8, while simultaneously, myeloid cells increase creatine production, supplying it to the tumor cells." (PMID 39769038, 2024). "These in vivo studies showed that mice injected with tumour cells with functional SLC6A8 presented severe disease and a higher amount of intratumour creatine as well as lower ROS levels." (PMID 36835201, 2023). "To explore the relationship between tumor immune microenvironment and SLC6A8, we applied R software package to evaluate the stromal, immune, and estimate scores." (PMID 36061183, 2022). "Next, we analyzed the relationship between SLC6A8 expression and scores of tumor-infiltrating immune cells based on data from TIMER database, and found that the most negatively related tumors were LUSC, SKCM and TGCT." (PMID 36061183, 2022). "Analysis of the ENSG00000130821 dataset in the EWAS Data Hub online database showed that methylation levels in LUAD and LUSC negatively correlated with SLC6A8 expression, and the methylation levels in tumor tissues were lower than those in normal tissues." (PMID 35251966, 2022). "In tumor cell enriched regions, SHB, VRK2, KRT6A, GRHPR, CGA, SLC6A8, and LY6D were associated with the survival of NPC patients (P < 0.05)." (PMID 36618352, 2022). "Evaluation of the LUAD TIME by the ESTIMATE algorithm revealed that the immune cell score was significantly lower in the SLC6A8 high-expression group than in the SLC6A8 low-expression group, while the opposite phenomenon was observed in terms of tumor purity." (PMID 35692837, 2022). "SLC6A8 expression was significantly higher in MSI-high tumor tissues than MSI-low ones in KICH, LUSC, STAD and TGCT." (PMID 36061183, 2022).
tumor (continued). "To investigate the effects of SLC6A8 on cellular pathways and functions, we conducted KEGG and GO enrichment analysis based on SLC6A8-associated genes in tumor." (PMID 36061183, 2022). "Higher levels of the creatine transporter protein Slc6a8 were expressed in TILs compared to T cells isolated from tumor-free spleens of the tumor-bearing animals." (PMID 33652752, 2021). "If SLC6A8 inhibition can reduce intracellular levels of phosphocreatine available for ATP synthesis in tumor cells, tumor cell growth and metastasis may potentially be limited." (PMID 40903981, 2025). "In this work, we focus on the transporters for taurine (TauT, SLC6A6) and creatine (CT-1, SLC6A8) as they could play important roles in tumour growth and development." (PMID 36835201, 2023). "Thereof, these results suggest that SLC6A8 might influence tumor progression via reshaping cellular metabolism." (PMID 36061183, 2022). "Collectively, those results indicate that SLC6A8 might be involved in the regulation of tumor immune microenvironment." (PMID 36061183, 2022). "In addition, the correlation of SLC6A8 expression with various tumor-infiltrating immune cells was further explored in 30 types of cancer." (PMID 36061183, 2022). "The results demonstrated that both paired difference and unpaired difference analysis of SLC6A8 in NSCLC showed statistical significance, and SLC6A8 expression was significantly higher in tumor tissues than in paraneoplastic (P-value<0.05) or normal tissues (P-value<0.05)." (PMID 35251966, 2022). "Immunohistochemistry was performed to detect SLC6A8 protein abundances in tumor tissues." (PMID 33990217, 2021). "Nonetheless, the implications of SLC6A8 in tumor progression remain poorly studied." (PMID 33990217, 2021). "In NSCLC, SLC6A8 may be involved in tumor progression through the Notch signaling pathway." (PMID 35692837, 2022). "Next, we evaluated the gene expression of SLC6A8 and CHKA in matched tumor/normal data for 57 AC and 49 SqCC cases from the TCGA consortium." (PMID 40903981, 2025). "In summary, hypoxia-induced upregulation of SLC6A8 promotes intratumoral creatine accumulation and preserves cellular redox homeostasis, which augments TNBC cell survival and tumor growth via activating AKT/ERK signaling cascade." (PMID 33990217, 2021). "Herein, we show that SLC6A8 is robustly induced by p65/NF-κB in hypoxic TNBC cells and aberrantly overexpressed in TNBC tumor tissues." (PMID 33990217, 2021). "SLC6A8 showed a consistent protein expression pattern, but not mRNA expression pattern, compared to the tumor tissue data, while CHKA did not." (PMID 40903981, 2025). "Notably, the mRNA expression of both SLC6A8 and CHKA matched the corresponding metabolite level in the tumor tissue." (PMID 40903981, 2025). "We found that SLC6A6 and SLC6A8 had higher expression levels in liver metastases than in normal pancreatic tissues and primary tumours." (PMID 37370109, 2023). "For the 11 types of cancer in which SLC6A8 expression in their corresponding normal tissues was lacking, the GTEx dataset in GEPIA2 website was used for comparison of SLC6A8 expression between tumor and normal tissue." (PMID 36061183, 2022). "As the MC38 cells do not express the creatine transporter Slc6a8, the action of CR was not directly on the tumor." (PMID 33652752, 2021). "No report supported SLC6A8 was related to tumor or metastasis, and SLC6A8 is not significantly enriched in gene sets related to cell motility, adhesion or EMT by GSEA." (PMID 33808696, 2021). "Besides, SLC6A8 had negative correlation with the levels of various tumor-infiltrating immune cells in pan-cancer." (PMID 36061183, 2022). "Using the other markers (SLC6A8, HJURP, CCNE2), the detection of the spiked-in tumor cells was not possible due to high background signal from PBMCs and the low expression in the selected three cell lines, which results in equal Ct values in spiked and unspiked samples." (PMID 36831613, 2023).
cancer (13 papers, 2015 to 2025). A tumor composed of atypical neoplastic, often pleomorphic cells that invade other tissues. "Cancer‐associated fibroblast (CAF)‐derived VTN upregulates SLC6A8 expression in colorectal cancer (CRC) cells and macrophages through enhanced FAK phosphorylation." (PMID 40538300, 2025). "In hypoxic TNBC cells, the activity of SLC6A8 mediated intracellular accumulation of creatine, which caused survival of cancer and decreased apoptosis by keeping homeostasis." (PMID 36835201, 2023). "SLC6A8 expression was inconsistently prognostic in different types of cancer, albeit associated with favorable survival in the vast majority of cancers." (PMID 36061183, 2022). "Here, we conducted a pan-cancer bioinformatics analysis of the expression and mutation profile, and clinical significance of SLC6A8 and its potential effect on malignancy." (PMID 36061183, 2022). "Kaplan–Meier survival curves of pan-cancer patients showed an adverse pan-cancer prognostic association of SLC6A8 expression." (PMID 36061183, 2022). "Our findings unprecedentedly revealed the potential prognostic and diagnostic value of SLC6A8 in pan-cancer." (PMID 36061183, 2022). "Bioinformatics analysis was performed to investigate the expression and mutation profiles of SLC6A8 in cancers, and the association of SLC6A8 expression with cancer patients’ survival and immune cell infiltration." (PMID 36061183, 2022). "The genetic alteration of SLC6A8, including mutation, amplification and deletion, was frequently present across various types of cancer." (PMID 36061183, 2022). "Furthermore, we investigated the association between SLC6A8 expression and the prognosis of cancer patients through bioinformatics analysis of the GEO dataset via the Prognoscan database." (PMID 36061183, 2022). "SLC6A8 has been reported to be closely associated with the development of cancer." (PMID 35692837, 2022). "Given the associations between SLC6A8 and various cancers, there is the possibility that it may serve as a biomarker." (PMID 35692837, 2022). "In addition, SLC6A8 was found to be a significant prognostic and diagnostic factor in various cancers." (PMID 36061183, 2022). "Thus, SLC6A8 is a potential factor contributing to modulation of the mutational landscape in various cancers." (PMID 36061183, 2022). "Notably, CD276 expression was remarkably associated with SLC6A8 in 11 of 32 types of cancer." (PMID 36061183, 2022). "The creatine transporter protein SLC6A8 imports the high‐energy metabolite phosphocreatine into the cell where it can be converted to ATP to fuel the survival of cancer cells as they proliferate and spread." (PMID 40903981, 2025). "Previous studies have shown that SLC6A8 inhibition prevents the uptake of phosphocreatine/creatine produced from the extracellular space CKB during cancer cell migration." (PMID 39769038, 2024). "SLC6A8 helps cancer cells collect energy via import and protects cancer cells from reactive oxygen species (ROS)." (PMID 39769038, 2024). "Herein, we present the potential role of taurine (SLC6A6) and creatine (SLC6A8) transporters in cancer development as well as therapeutic potential of their inhibitors." (PMID 36835201, 2023). "Downregulation or upregulation of SLC6A8 activity influenced different cell cycle stages of cancer: G1 and S, respectively." (PMID 36835201, 2023). "Data analysis showed that the SLC6A8 gene was upregulated under hypoxia, which suggests that creatine can function as an antioxidant molecule in cancer cells." (PMID 36835201, 2023). "On the other hand, overexpression and increased activity of SLC6A6 or SLC6A8 proteins were described in several types of cancer." (PMID 36835201, 2023). "In spite of the fact that numerous public databases have been integrated to clarify the role of SLC6A8 in pan-cancer, several limitations to the present work should be pointed out." (PMID 36061183, 2022).